OR8U3 (olfactory receptor family 8 subfamily U member 3)
Description:
Odorant receptor.
Synonyms: OR5R1; OR5R1P; OR11-185
Tractability: Antibody: UniProt places it where antibodies can reach, with medium confidence; UniProt predicts a signal peptide or a membrane-spanning region; its Gene Ontology location is reachable by antibodies, with medium confidence.
Gene: Protein-coding gene on chromosome 11 (56,417,258 to 56,418,232, reverse strand). Ensembl gene ENSG00000279961.
Subcellular location: Cell membrane
Pathways (Reactome):
Sensory Perception: Expression and translocation of olfactory receptors
Gene Ontology:
Molecular function: olfactory receptor activity; G protein-coupled receptor activity
Biological process: G protein-coupled receptor signaling pathway; sensory perception of smell; detection of chemical stimulus involved in sensory perception of smell
Cellular component: plasma membrane; membrane
Genetic constraint (gnomAD): Missense variants: 385 observed, 371.45 expected, observed/expected ratio (o/e) 1.04, 90% interval 0.95 to 1.13. Synonymous variants: 158 observed, 140.03 expected, observed/expected ratio (o/e) 1.13, 90% interval 0.99 to 1.29.
Homologues: Orthologues: dog OR8U3 (90% identical), rabbit OR8U3 (89% identical), rat Or8u3 (89% identical), guinea pig OR8U3 (85% identical), mouse Or8u3 (81% identical). Paralogues in human: OR8U1 (65% identical), OR8J2 (56% identical), OR8K3 (55% identical), OR8K5 (55% identical), OR8J1 (55% identical), OR8J3 (54% identical), OR8K1 (54% identical), OR5B12 (53% identical), OR5M11 (53% identical), OR8G5 (53% identical), OR5AP2 (52% identical), OR5AR1 (52% identical), and 84 more.